LAG3 (lymphocyte activating 3)
Diseases named in the same sentence as LAG3 in open-access papers (continued):
Sharing a sentence is not in itself a finding about the gene and the disease.
tumor (continued). "Lymphocyte activation gene 3 (LAG3) is a T cell inhibitory receptor that promotes tumor cell immune escape and is a potential target for cancer diagnostic and immunotherapeutic applications." (PMID 36278613, 2022). "Increased levels of LAG-3, methylation and tumor cell-intrinsic protein expression were correlated with overall survival." (PMID 36077354, 2022). "Gal-3 causes suppression of activated antigen-committed CD8 T cells through LAG-3 expression in the tumor microenvironment and inhibits the extension of plasmacytoid dendritic cells." (PMID 36359346, 2022). "In our prior studies, most tumor-specific T cells diverged into Lag3+ TEX in PDA or remained Klrg1+ functional cytotoxic T cells in the spleens of tumor-bearing mice." (PMID 35393950, 2022). "The activity and expression level of the LAG-3 molecule increases on the surface of TIL cells with the development of tumours." (PMID 35494015, 2022). "Like PD-1, CTLA4 is an inhibitory receptor that prevents CD28-mediated co-stimulatory signals for immune response, while LAG3 contributes to a state of T cell dysfunction in the tumor microenvironment." (PMID 36354714, 2022). "LAG-3 expression was highly correlated with CD8A gene expression in the TCGA-SARC cohort and the predominant expression of LAG-3 by tumor-infiltrating CD8+ T cells was then confirmed by IHC." (PMID 36230502, 2022). "The LAG-3 inhibitor relatlimab has been shown to deplete leukemia cells and restore NK and T cell–mediated anti-tumor activity in chronic lymphocytic leukemia." (PMID 36225938, 2022). "A moderate correlation between frequencies of FoxP3+Helios+ Tregs and CD4+LAG-3+ T cells in in circulation was stronger in advanced tumor stages, compared to early stages (r = −0.146, p = 0.631 [early]; r = 0.478, p = 0.044 [advanced])." (PMID 36146549, 2022). "Since the novel tribodies targeting PD-L1, PD-1 and LAG-3 efficiently induced the activation of lymphocytes, we further investigated their antitumor effects on co-cultures of tumor cells and lymphocytes." (PMID 35408827, 2022). "The CD103+CD39+CD8+ TRM cells in tumor implants tended to have higher PD-1 and LAG-3 expression than CD103+CD39−CD8+ TRM cells, suggesting the possibility of distinguishing the activation state of TRM cells via CD39 expression." (PMID 35740548, 2022). "The emergence of FGL1 as a major functional ligand of LAG3 has attracted great attention in the field of tumor immunotherapy." (PMID 34975333, 2022). "This study demonstrated a prognostic value of higher expression of TIM-3, PDL1- LAG3, and PD1 at the tumor associated with poor survival, while high expression at the stroma correlated with improvement of 10 years of survival." (PMID 36013315, 2022). "The features suggested that HL tumor cells escaped from immunosurveillance for their survival and growth, including CTLA-4, PD-1, and LAG-3-associated immune evasion." (PMID 36035394, 2022). "Blockade of the FGL1/LAG3 axis with concurrent administration of metformin can enhance T-cell-mediated immune response, improve the tumor microenvironment immunosuppression, and enhance general anti-tumor immunity." (PMID 34975333, 2022). "LAG-3, mainly found on activated immune cells, leads to immune escape of tumor cells similar to that of PD-1." (PMID 35135556, 2022). "The combination therapy of anti-LAG-3 antibody and tumor-associated antigen inoculation increases CD8+T cells in the TIME and destroyed tumor parenchyma in prostate cancer tumor models." (PMID 35874717, 2022). "Recently, multiple ICPs are investigated as novel targets in experimental tumor models or in clinical trials, like LAG3, TIM-3, TIGIT, BTLA and/or agonists of the co-stimulatory receptors GITR, OX40, 41BB and ICOS." (PMID 35185904, 2022). "The activation of pDCs by LAG-3 occurs at tumor sites and is partly responsible for directing the immunosuppressive environment." (PMID 36077354, 2022).
tumor (continued). "It is possible that the engagement of LAG-3 by FGL1 in the tumour micro-environment prevents an effective anti-cancer immune response." (PMID 35265944, 2022). "In patients with lung adenocarcinoma (LUAD) higher numbers of LAG-3+ cells are correlated with features of aggressive tumor character, including predominantly solid histology, the presence of lymphovascular invasion and nodal metastases." (PMID 36077354, 2022). "More profoundly, the co-blockade of LAG3 in tandem with TIGIT affected additional tumor control, translating to a survival rate of 37.5% in mice." (PMID 36123677, 2022). "Further, the expression level of immune checkpoint molecules (PDL1, CTLA4, LAG3, TIGIT, CD27, IDO1, ICOS) and tumor mutational burden (TMB) also showed significant differences between the two subtypes, indicating the clinical value of the two subtypes." (PMID 36568197, 2022). "High LAG-3 expression on tumor infiltrating lymphocytes (TILs) and peripheral blood lymphocytes (PBLs) is associated with the suppression of EBV-specific T cell function." (PMID 36077354, 2022). "LAG-3 and PD-L1 are often found to be co-expressed on tumor-infiltrating T cells, and dual blockade of LAG-3 and PD-1 has shown synergistic anti-tumor efficacy in preclinical studies." (PMID 36230766, 2022). "The interaction between LAG3 and its ligands promotes tumor escape from apoptosis through the recruitment of tumor-specific CD4+ T cells (through the interaction with MHC class II) and the inhibition of CD8+ T cells’ cytotoxic function by Gal-3 binding." (PMID 36230566, 2022). "We found that mice with larger tumours had a higher proportion of intratumoral PD-1+LAG3+TIM3+ CD8+ T cells and greater hypersensitivity to thermal pain (not shown)." (PMID 36323780, 2022). "We next compared normalized LAG3 counts across matched-pair samples as tumor stage became progressively more advanced (normal kidney ➔ primary tumor; primary tumor ➔ metastases)." (PMID 36313654, 2022). "Its binding also induces PD-1 and LAG-3 degradation, and preclinical data show improvement for the treatment of tumor models resistant to PD-1 blockade monotherapies." (PMID 35755891, 2022). "In each model, the anti-tumor efficacy of vaccination was increased with PD-1 and/or LAG-3 blockade." (PMID 36015348, 2022). "LAG-3 and PD-1 were highly co-expressed in CD4+T cells and CD8+T cells, and the inhibitory effect of the blocking of LAG-3 and PD-1 on tumor progression." (PMID 35874717, 2022). "Loss of MHC Class I expression, T cell anergy, and expression of the inhibitory receptors PD-1, LAG-3, and TIM-3 are all caused by the immune-suppressive mechanisms in the tumor microenvironment, which contribute to T cell exhaustion." (PMID 36298592, 2022). "We show that blocking immune checkpoints (PD1, LAG3), alone and in combination, can enhance effector T-cell responses in the tumor microenvironment of MM patients to a greater extent than by stimulating costimulatory molecules (OX40, GITR)." (PMID 34290359, 2022). "The costimulatory signals generated by myeloid tumor cells can induce T cell “exhaustion” through the upregulation of immune checkpoint proteins, such as PD-1, LAG3, and TIM3, thereby resulting in the development of advanced immune escape strategies." (PMID 35265454, 2022). "Tumor-infiltrating Tregs generally express higher levels of cell surface molecules associated with T cell activation, such as CD25, CTLA-4, PD-1, LAG3, TIGIT, ICOS, 4-1BB, OX-40, and GTFR." (PMID 34417572, 2022). "As the activation of LAG3 has an inhibitory effect on T cells, the use of anti-LAG3 inhibitors to activate the immune system and kill tumor cells represents another potential immunotherapeutic strategy." (PMID 36042469, 2022). "Here, in cDC1-deficient hosts, CD40 agonist primed tumor-specific T cells that coexpressed Klrg1 and Lag3, or a Treg marker Foxp3, and these T cells appeared dispensable for tumor control." (PMID 35393950, 2022).
tumor (continued). "LAG3-MHC-II binding additionally recruits tumor-specific CD4+ T cells, decreasing the CD8+ T cell response." (PMID 35345849, 2022). "Significantly, targeting STAT3 induced anti‐HCC immune memory and accumulation of the important antitumour effector CD8+ T cells in tumour tissues, which expressed low levels of checkpoint molecules such as LAG‐3 and PD‐1." (PMID 35665592, 2022). "LAG3 protein was expressed on the tumor-infiltrating lymphocytes (TILs) in 15 out of 20 (75%) samples." (PMID 36119473, 2022). "LAG-3 has been regarded as an indicator of tumor prognosis and become a novel tumor immunotherapy target beyond PD-1/PD-L1 and CTLA-4." (PMID 35958563, 2022). "Another study reported that TIGIT-positive NK cells infiltrating mouse subcutaneous tumours or human endometrial cancers were found to co-express other inhibitory receptors, such as LAG-3 and TIM-3, and their functions were altered." (PMID 35328510, 2022). "Next, we assessed the LAG3 expression in the distant tumor environment after MWA treatment in the MC38 tumor model established as in our previous work." (PMID 36180876, 2022). "An increased tracer uptake was observed in lymph nodes and tumor when mice were treated with PD-1 inhibitors, due to increased LAG-3 expression on TILs." (PMID 35625811, 2022). "Suppression of tumour growth was associated with a reduced expression of immune checkpoint molecules, PD-1, TIGIT and LAG-3 with upregulation of CXCR3 expression." (PMID 36104795, 2022). "Representative flow cytometric plots examining co-expression of PD-1 and LAG3 revealed a substantial population of PD-1+LAG3+ CD8+ T cells infiltrating the tumor in all groups." (PMID 36211806, 2022). "For HL, combined blocking of LAG-3 and PD-1 has stronger anti-tumor immunity mediated by CD4+T cells than single treatment." (PMID 36561512, 2022). "The interaction between FGL1 and LAG-3 mutually promotes tumor immune escape through inhibiting the activation of antigen-specific T cell." (PMID 35958563, 2022). "Typically, LAG-3 and PD-1 expressions were greater in the tumor, while CX3CR1, CXCR3, and CD27 expressions were lower compared to the PB levels." (PMID 35003893, 2022). "While blocking antibodies directed against LAG-3 and PD-L1 were sufficient to induce senescence in tumor cells, a combination with an adoptive transfer of TAA-specific Th1 cells further increased this effect." (PMID 35326515, 2022). "The prognostic role of LAG3 is controversial and seems to be dependent on the tumor entity, treatment type, levels of TILs, site of expression (intraepithelial vs. invasive tumor margin vs. tumor stroma) and co-expression of other ICs." (PMID 36376922, 2022). "The other ligands for LAG-3 are LSECtin and Galectin-3 derived from tumor and tumor stromal cells, respectively." (PMID 36077354, 2022). "The combination of anti-LAG-3 and anti-PD-1 therapies, evaluated in clinical trials can significantly enhance the anti-tumor effect." (PMID 36077354, 2022). "Only a small amount of PD-1 and LAG-3 were expressed in tumor cells, with positive rates of 4.0% and 2.9%, respectively." (PMID 36561512, 2022). "In cancer therapy binding between LAG-3/MCH-II triggers anti-immune response including tumor escape, decreased production of cytokines, and a reduction in CD8+ T cells response." (PMID 36059606, 2022). "Herein, we aim to describe the structure and the known ligands of LAG-3 and summarize the immune-regulatory effects on active T cells in tumor microenvironment, as well as the LAG-3 inhibitors which have been evaluated in the clinic." (PMID 35958563, 2022). "Subsequently, the combined antitumor effect of a LAG-3 inhibitor and PD-1 inhibitor was found in mouse tumor models of ovarian cancer and chronic lymphocytic leukemia." (PMID 35892835, 2022). "Effective inhibition of the FGL1/LAG3 axis can activate tumor T cell immunity, which provides a meaningful direction for tumor immunotherapy." (PMID 34975333, 2022).
tumor (continued). "Several clinical trials have shown the potential role of LAG-3 inhibitors as an adjuvant therapy for melanoma, prostate and metastatic breast cancer, with tumor response rates of 50%." (PMID 34371708, 2021). "Blockading the interaction of FGL1 and LAG-3 can trigger T cells and restore anti-tumor immunity by facilitating the TCR/CD28 signaling pathway." (PMID 33867830, 2021). "There was a strong and significant positive correlation (r = 0.81) between the percentage of OAC tumour cells expressing LAG-3 and treatment response (p = 0.03) in the treatment-naïve setting." (PMID 33765543, 2021). "LAG-3-specific nanobodies were developed and radiolabeled to assess LAG-3 expression in tumor-bearing animals." (PMID 33925941, 2021). "The upregulation of LAG3 is essential for limiting T cell activation and preventing the start of tumor immune responses in cancers." (PMID 33490273, 2021). "The role of LAG3 in immune regulation, including the generation of effective anti-tumour immune responses remains poorly understood." (PMID 33824480, 2021). "Gal-3 shapes antitumor-specific immune responses by suppressing activated antigen-committed CD8 T cells via LAG-3 expression in the tumor microenvironment and inhibiting expansion of plasmacytoid dendritic cells." (PMID 34067904, 2021). "In other words, some degree of primary anti-cancer immune response is required in order to achieve an anti-tumour effect of PI3Kδ and LAG3 combination therapy." (PMID 33824480, 2021). "Novel immune checkpoints (such as TIM-3 and LAG-3) have been analyzed as potential targets, due to their responsibility in lymphocyte exhaustion and tumor immune evasion." (PMID 34885091, 2021). "Further, the CD4pos Th1 population (T_C9) displayed reduced expression of exhaustion/dysfunctional marker, LAG3 suggesting that T cell populations in Osm−/− tumours remain more functional and less exhausted." (PMID 34921158, 2021). "LAG-3 also interacts with galectin-3 (GAL3) and liver sinusoidal endothelial cell lectin expressed on tumour cells and tumour-associated stromal cells, respectively." (PMID 33921181, 2021). "In recent years, it has been shown that tissue-resident T lymphocytes can overexpress PD-1 and other immune checkpoint molecules, such as TIGIT, LAG-3, and Tim-3, in some experimental animal and human tumor tissues." (PMID 35096624, 2021). "TIGIT was also highly expressed in MEL04 tumor-infiltrating T cells compared with other co-inhibitory checkpoint molecules such as LAG-3 and TIM-3." (PMID 34795004, 2021). "There was only one LAG3-positive tumor (0.8%) with more than 4% LAG3-positive TILs, 29.0% of tumors had low-LAG3-expressing TILs, and 70.2% of tumors showed no LAG3-positive TILs." (PMID 34072549, 2021). "LAG-3 positive Tregs occur in primary tumours, in lymphocytes of tumour-invaded lymph nodes, and in lymphocytes infiltrating visceral metastases, and produce immunosuppressive cytokines, IL-10 and TGF-β." (PMID 34968365, 2021). "LAG3 is a molecule involved in blocking tumor cell proliferation and regulating the production of IFN-γ and TNFα cytokines." (PMID 34575678, 2021). "Tumor infiltrating T cells constantly exposed to the antigen, express LAG-3 and also multiple other co-receptors, which results in their exhaustion." (PMID 34356899, 2021). "This interaction normally prevents tissue damage and autoimmunity, however, tumor-infiltrating lymphocytes (TILs) found in the TME upregulates LAG-3 thereby promoting cell dysfunction, immune exhaustion and favorable conditions for tumor growth." (PMID 34268109, 2021). "T cell immunoglobulin and mucin domain protein 3 (TIM-3), similarly to LAG-3, is an inhibitory receptor frequently detected upregulated on NSCLC TILs during tumor progression and is associated with an exhausted, burned phenotype of TILs and resistance to ICI." (PMID 35069581, 2021).
tumor (continued). "LAG-3 is an immune checkpoint receptor that negatively regulates T cell-mediated responses by inducing an hyporesponsive state, thus promoting tumor escape." (PMID 33925565, 2021). "As LAG3 on T lymphocytes binds to ligands on APCs or tumour cells, we subsequently analysed which tumours express these ligands." (PMID 34503258, 2021). "CSF-1R+ carcinoma cells are significantly associated with stromal tumor-infiltrating lymphocytes; intraepithelial lymphocytic infiltrates expressing CD8, FOXP3, TIM3, LAG3, and PD-1; and PD-L1+ carcinoma cells (p < 0.001)." (PMID 34830923, 2021). "This can be explained by the high percentage of PD-L1+ and LAG-3+ TILs that we observed after harvesting the tumor and spleen." (PMID 33466653, 2021). "In an ovarian cancer model, a synergistic anti-tumor effect of combinatory treatment of LAG3 and PD1 mAb shed light on future potential combination therapies." (PMID 34771459, 2021). "LAG-3 expression was associated with the presence of CD3+ (p = 0.029), CD8+ (p = 0.001), PD-1+ (p < 0.001) TILs and PD-L1+ tumor cells (p = 0.021), respectively." (PMID 33651248, 2021). "Analysis of tumor uptake showed that only radiolabeled LAG-3 single-domain antibody accumulated in MC38 tumors, with little increase in larger tumors (P = 0.0364 and P = 0.0091 for day 11 and 17 tumors, respectively)." (PMID 33712537, 2021). "There are also studies on the potential role of other checkpoints in tumor immune regulation, such as lymphocyte activation gene-3 (LAG-3), T cell immunoglobulin-3 (Tim-3), T cell immunoglobulin and the ITIM domain (TIGIT)." (PMID 34925375, 2021). "LAG-3 is expressed on exhausted T cells and interacts with tumor cells to inhibit cytotoxic T cell signaling." (PMID 34277428, 2021). "This growth factor, which is also abundantly produced by RCC tumor cells, activates the expression of three CD8+ T cell checkpoint receptor genes, encoding lymphocyte activation gene-3 (LAG3), T-cell immunoglobulin mucin-domain containing-3 (TIM-3) and PD-1." (PMID 33676416, 2021). "Consistently, dual blockade of PD-1 and LAG-3 significantly inhibited the growth of tumours compared to control mice." (PMID 33809369, 2021). "For example, LAG-3 has been reported positive expression on the surface of tumor-infiltrating lymphocytes (TILs) of multiple cancers, correlating with aggressive clinical features." (PMID 34721517, 2021). "LAG3 expression can be measured using IHC, as demonstrated across multiple tumour types, with positivity described as >15 LAG3 positive TIL per 40x magnification hot spot field." (PMID 34830795, 2021). "In chronic lymphocytic leukemia (CLL), immunotherapy, such as anti-PD1/CTLA-4 immunotherapy, shows little benefits in patient survival, and the higher expression of LAG3 in CLL contributes to tumor immune escape, as well as indicates poor prognosis." (PMID 35111155, 2021). "Most combination therapies involve the combination of anti-LAG3 and anti-PD-1 therapies, which can significantly enhance the anti-tumor effect." (PMID 35111155, 2021). "With tumor progression, other immune checkpoints are sequentially upregulated, with PD-1 upregulated as an early event, while LAG-3 and BTLA upregulated as a late event." (PMID 34194441, 2021). "MHC-II binds to a conservative extension loop in the D1 domain of LAG-3 protein and transmits inhibitory signals through its cytoplasmic domain, thus promoting tumor immune escape." (PMID 34943817, 2021). "LAG3 is highly expressed by activated human T and NK cells, as well as by tumor infiltrating lymphocytes (TILs), in various tumors." (PMID 34267742, 2021). "A positive correlation was found between the amount of LAG-3 single-domain antibody tracer in the tumor and the LAG-3 levels on CD8+ T cells, CD19+ B cells, and F4/80+ macrophages." (PMID 33712537, 2021).